SOX2 (SRY-box transcription factor 2)
Diseases named in the same sentence as SOX2 in open-access papers (continued):
Sharing a sentence is not in itself a finding about the gene and the disease.
tumor (continued). "Of those, eight (HOXA3, HOXA5, ATP10A, SOX2, MIR922, ADAMTSL1, KHDRBS2, and LITD1) were hypermethylated in at least one LS tumor group like here in FAP normal, whereas NEDD4L, and FOXP1 were hypermethylated in LS carcinomas and here in LS normal." (PMID 40753397, 2025). "WB and IHC tests in tumor tissues further confirmed that the protein expression of p-AKT and SOX2 decreased when MK2206 was added." (PMID 39994220, 2025). "This reduced efficacy is attributed to an increase in SOX2 expression following ADT, which subsequently activates the CIGG pathway that can promote further tumor development." (PMID 39976818, 2025). "Together, these findings indicate that SOX2 maintains the glial progenitor-like signature and promotes NOTCH-driven CP tumor growth." (PMID 40128799, 2025). "SOX2, PIWI proteins, and MALAT1 have been identified as potential regulators of tumor progression, offering promise for their application as plasma-based biomarkers." (PMID 40674376, 2025). "SOX2 and OCT4, two pivotal stem cell transcription factors, exert significant influence on tumor initiation and progression." (PMID 39781344, 2025). "Western blot analysis of tumor tissues revealed elevated expression of CD133, CD15, Nestin, Sox2, and Klf4 in mice implanted with CD133−CD15− cells treated with TMZ compared to controls without TMZ treatment." (PMID 40253386, 2025). "The change of SOX2 expression is also observed in the mucosa surrounding the tumor, suggesting that, similarly to CDX2 changes, SOX2 changes precede the development of cancer." (PMID 40149431, 2025). "Its upregulation enhanced tumor growth, invasion, epithelial-mesenchymal transition, and stem-like characteristics by increasing key markers (CD44, EpCAM, SOX2, and Nanog)." (PMID 40290725, 2025). "FOXM1 has been implicated in various hallmarks of cancer, including cell cycle progression and regulation of the tumour microenvironment as well as in LUSC progression and in the regulation of SOX2 transcription." (PMID 41388088, 2025). "Despite relatively low SOX2 expression in this CPC, some tumor cells exhibited co-expression of SOX2 and NOTCH genes." (PMID 40128799, 2025). "As a key pluripotency factor, OCT4 works with SOX2 and NANOG to sustain an undifferentiated, stem-like state, preventing normal differentiation processes and driving tumor progression." (PMID 40722714, 2025). "FVTF significantly reduced the ability of tumorsphere and soft agar colony formation, the levels of CD44 protein and BMI1, OCT4 and SOX2 mRNAs in HCC cells, and in vivo tumor initiation ability of HCC cells." (PMID 40050970, 2025). "In particular, Wi-N and TEG caused a stronger reduction in the self-renewal capability of CSCs than Wi-A, as evidenced by a tumor spheroid formation assay and analyses of stemness-related genes (ALDH1, CD44, NANOG, CD133, SOX2)." (PMID 39859209, 2025). "Immunofluorescent microscopy confirmed nuclear SOX2 accumulation and co-expression of SOX2 and HIF-1α in dedifferentiated CSC-like cells, demonstrating tumor heterogeneity." (PMID 40358200, 2025). "We reported pre‐clinical evidence for successful and prolonged tumor growth inhibition in HNC achieved by Cas9 mRNA and guide against SOX2 administered intratumorally via EGFR‐targeting LNPs." (PMID 39736115, 2025). "The selection of ROIs was guided by immunofluorescence-based morphology marker staining for SOX2, IBA1, and GFAP, and ROIs were chosen based on the highest tumor cell density." (PMID 40960500, 2025). "Low levels of KLF4, c-MYC, and NANOG and high expressions of SOX2 and OCT4 in tumor tissue correlated with poor overall survival (OS) and disease-free survival (DFS), respectively." (PMID 41463190, 2025). "In agreement, knockdown of Sox2 markedly decreased LMX1A and LMX1B expression in NOTCH-driven CP tumor cells." (PMID 40128799, 2025).
tumor (continued). "Utilizing a published scRNA-seq dataset comprising 15 tumor samples and one nasopharynx, UMAP visualization revealed that SOX2, NTRK2, LRP6, and PTPRZ1 from our candidate list were predominantly expressed in epithelial and malignant patient cells." (PMID 40133476, 2025). "Upon entering the tumor cells, DCLX069 was rapidly released from the DNM in response to elevated intracellular GSH levels, leading to a robust modulation of the PRMT1/SOX2 axis." (PMID 41377018, 2025). "SOX2 and OCT4 are vital transcription factors that play pivotal roles in the self-renewal and differentiation processes of tumor cells." (PMID 39781344, 2025). "This study is especially important for CSC-marker research because it suggests that recurrence-specific tumor biology influences the prognostic implications of NANOG and SOX2." (PMID 40227667, 2025). "In agreement, SOX2 is critical in regulating the expression of LMX1A and LMX1B in tumor cells as well as progenitors in the rhombic lip, whereas LMX1A and LMX1B mediate SOX2 functions in tumor cells." (PMID 40128799, 2025). "Exposure of tumor cells to such conditions involves a metabolic adaptation and a canonical upregulation of stem cell genes (CD133, Nestin, SOX2)." (PMID 41562896, 2025). "Remarkably, when selecting only the tumour cells in the dataset, we also observed a similar expression pattern in NPC signature (based on SOX2, NES, and ASCL1 genes) and SSTR2, supporting the putative relationship between this NPC population and SSTR2 levels." (PMID 40268793, 2025). "We observed that Rha promoted the apoptosis of SCC9‐CisR cells and inhibited their tumor sphere‐forming ability, accompanied by reduced CD44 and SOX2 mRNA levels." (PMID 40608530, 2025). "By categorizing the perivascular region into two distinct zones based on their proximity to tumor cells—far and close—it was found that stemness markers (CD15, CD133, SOX2, NES, and NANOG) exhibited higher expression levels in regions closer to blood vessels." (PMID 41041071, 2025). "Under hypoxic conditions, HIF-1α can stimulate the expression of SOX2 and OCT4, thereby facilitating tumor cell self-renewal and differentiation processes." (PMID 39781344, 2025). "Immunofluorescence staining further confirmed decreased expression of stemness markers SOX2 and ALDH1 in USP20‐silenced tumours compared to controls." (PMID 41261048, 2025). "In our study patients with OSCC show lower levels of SOX2 and SOX9 in lymph node metastases while patients with tumor recurrence have significantly higher expression levels." (PMID 39180200, 2025). "Regarding tumor capacity to grow, infiltrate and resist apoptosis after PDT, we assessed the expression of vimentin, nestin and SOX2 by immunofluorescence." (PMID 41009470, 2025). "In the later stage, the expression and function of these tumor suppressor genes are diminished and endogenous expression of stemness genes such as OCT4, SOX2, NANOG, or other pluripotent genes is induced, leading to complete reprogramming into full-iPSCs." (PMID 40689085, 2025). "In tumor organoid models, it was found that TACSTD2 and SOX2 formed a positive feedback loop in TACSTD2high luminal cells, together driving neuroendocrine differentiation and castration resistance." (PMID 40821114, 2025). "The percentages of SOX2‐, OLIG2‐, and Ki67‐positive cells in the six tumor specimens demonstrated that this heterogeneity was highly similar to that of the corresponding parental tumors." (PMID 40112194, 2025). "In tumor cells, elevated lactylation enhances expression of glycolytic enzymes (e.g., LDHA, PKM2) and stemness-related genes (e.g., SOX2, NANOG), contributing to metabolic reprogramming and cancer progression." (PMID 41583433, 2025). "SOX2 can also induce epithelial-mesenchymal transition (EMT) by regulating ZEB1, N-cadherin, and other factors, thereby enhancing tumor cell migration and invasion and promoting metastasis." (PMID 41358198, 2025).
tumor (continued). "At the conclusion of the study, we observed enhanced tumor growth and upregulation of CD133 and SOX2 in xenografts derived from co-cultured GBM cells." (PMID 41041071, 2025). "Specifically, genes such as SOX2 and TOP2A displayed hypomethylated m6A modifications, with both genes being upregulated in tumor tissues." (PMID 41209572, 2025). "Lower SOX2 and SOX9 expression levels are required in lymph node metastases while high‐expression levels provide an advantage in tumor recurrence." (PMID 39180200, 2025). "The miRNA-148a and miRNA-152-3p can synergistically inhibit the expression of stemness markers, such as SOX2 and OCT4, inhibit tumor migration and invasion, and promote cell apoptosis." (PMID 39711287, 2025). "Biologically, ASCL1 plays a crucial role in tumor initiation and maintenance by regulating MYCL, SOX2, RET, BCL2, and DLL3, all of which contribute to NE differentiation and tumor survival." (PMID 40333678, 2025). "PRMT8 also influences pluripotency factors like Nanog, OCT4, and SOX2, promoting colon CSC phenotypic transformation and tumor progression." (PMID 41204384, 2025). "Conversely, subjects presenting increased expressions of SOX2 and OCT4 in tumor showed lower OS rates (log-rank, p = 0.004)." (PMID 41463190, 2025). "Tumor-associated macrophages and fibroblasts secrete cytokines that transform normal tumor cells into CSCs via TGF-β1, STAT3/Sox2, JAK2/STAT3/snail, notch/STAT3, and IGF-II/IGF1R pathways." (PMID 39753364, 2025). "Cancer stem cells express pluripotency markers such as OCT4, SOX2, and NANOG, maintaining self-renewal and adaptability, which are critical for the aggressiveness of the tumor." (PMID 39857670, 2025). "Abnormal expression of transcription factors SOX2 (SRY-related HMG-box gene 2), NANOG, and OCT4 is known to have different functions in tumor initiation and metastasis." (PMID 40227667, 2025). "This analysis identified a collection of genes both induced by Oct4 and Sox2 and enriched in GBM compared to non-tumor brain tissue." (PMID 40277917, 2025). "SOX2 is a critical regulator in GBM that influences key developmental pathways and contributes to tumor progression." (PMID 40628732, 2025). "Upon entering the tumor cells, DCLX069 is rapidly released from the DNM due to high intracellular GSH levels, leading to swift regulation of the PRMT1/SOX2 axis." (PMID 41377018, 2025). "SOX2 and NKX2‐1, as pivotal lineage‐defining TFs in lung epithelium, exert a decisive influence on the regulation of tumour cell fate." (PMID 40847555, 2025). "CSC biology is regulated by interconnected networks, including pluripotency transcription factors (OCT4, SOX2, Nanog, KLF4, Myc), intracellular signaling pathways (Wnt, NF-κB, Notch), epigenetic mechanisms, the tumor microenvironment, and EMT processes." (PMID 41204384, 2025). "Our results also revealed that SOX2 and NANOG were highly expressed in ESCC, and their expressions were correlated with lymph node metastasis and the late pathological stage of the tumor." (PMID 40626009, 2025). "The presence of cancer stem cells in the tumour tissue is further substantiated by increased expression of embryonic-specific transcription factors such as OCT4, SOX2, Nanog, cMYC and KLF4 in tumour tissues." (PMID 40433700, 2025). "In this context, understanding the prognostic roles of pluripotency transcription factors, particularly SOX2 and NANOG, in re-OSCC is critical, given their established links to CSC biology and tumor progression." (PMID 40227667, 2025). "SOX2 and PIWI expression in plasma showed a strong correlation with Ki-67 staining, a marker of tumor cell proliferation." (PMID 40674376, 2025). "- Plasticity: Ability to shift differentiation states.- Pluripotency Markers: Expression of OCT4, SOX2, and NANOG.- Self-Renewal: Maintains tumor’s aggressive behavior and adaptability." (PMID 39857670, 2025).
tumor (continued). "Sox9 inactivation was notably correlated with the increased expression of SOX2, suggesting SOX9 inactivation plays a role in promoting tumor progression in part by SOX2 upregulation." (PMID 40179020, 2025). "This same region also contains the Sox2 target ST6GAL1, suggesting that coamplification of Sox2 and ST6GAL1 further intensifies ST6GAL1 expression in the tumor." (PMID 40885395, 2025). "Next, we conducted qRT-PCR and WB experiments, which demonstrated positive correlations between levels of USP15 and those of molecules related to tumor stemness (CD133, EPCAM, SOX2, ALDH1 and OCT4)." (PMID 39794359, 2025). "Three were canonical oncogene drivers, namely HOXC11, SOX2, and KCNJ5, while the rest 25 are putative oncogenes and putative tumor suppressors in almost equal measure." (PMID 39484215, 2024). "Immunoblot of tumor bulk protein and in situ immunohistochemistry indicated that MIR31HG ASO therapy downregulated expression of GLI2, ABCG2, and SOX2." (PMID 37950038, 2024). "We assessed tumor cell heterogeneity with respect to N1-ICD and SOX2 protein expression in 4 different xenograft models, two GSI-sensitive (MB157 and HCC1599) and two NOTCH-independent (MB157R and HCC1806)." (PMID 39478150, 2024). "Blocking Notch signaling would result in derepressed SOX2 expression, driving a more invasive and GSI-resistant form of tumor growth, as shown in the MB157 model." (PMID 39478150, 2024). "Cell survival, tumor sphere formation and the SOX2 and SOX9 expression were analyzed in the cells silenced for SOX2 or SOX9 and compared to control cell lines." (PMID 38275880, 2024). "In TCGA-HNSCC, clinical characteristics were found to differ between groups with opposite expression levels of SOX2 and SOX9, with significance observed for gender, HPV status, tumor location, and radiation treatment." (PMID 38275880, 2024). "The role of SOX2 in HNSCC is controversial, while it appears to have an oncogenic role in the formation of the tumor; its expression is likely modulated during the tumor evolution." (PMID 38275880, 2024). "Tumor sphere formation, ALDH activity, and the expression levels of stemness-related factors (SOX2, BMI1, and CD133) in PCa cells were potently reduced after BHB treatment." (PMID 38555451, 2024). "And the expressions of tumor proliferation markers Ki67 and tumor stemness markers (NANOG, CD133, OCT4, and SOX2) all obviously reduced compared with the controls." (PMID 39692209, 2024). "MiR-145 is a well-known tumor suppressor, that inhibits the expression of ZEB1, a critical regulator of EMT, and embryonic transcription factors, Lin28, Nanog, OCT4, and SOX2 in a variety of cancer models." (PMID 39170516, 2024). "Hinokitiol led to tumor spheroids shrinkage as inhibited BC stem-like cells self-renewable capacity, suppressed tumor stemness-progression via inhibiting CD44/Nanog/SOX2/Oct4 signaling pathways." (PMID 38612715, 2024). "Nuclear expression of BMI1 and SOX2 and cytoplasmic or membranous staining of CD166 was seen in the tumor parenchyma, while mainly nuclear and occasionally cytoplasmic expression of OCT4 was observed in both parenchymal and stromal cells of MEC in most cases." (PMID 39858584, 2024). "231DD shows enhanced expression of ES-TFs SOX2, MYC, and NANOG and tumor sphere formation compared to vector control 231 cells." (PMID 38886396, 2024). "To evaluate tumor heterogeneity, we performed immunohistochemistry staining for N1-ICD, SOX2, the SC marker CD49f and the EMT marker SLUG on tumor sections of the four TNBC xenograft models." (PMID 39478150, 2024). "MLL4 regulates the PI3K/AKT/SRY-related SRY-related HMG-box gene 2 (SOX2) signaling pathway in NSCLC cells, diminishing its role in inhibiting tumor growth and metastasis." (PMID 38525426, 2024). "These cells rely on expression of stem cell transcription factor genes including SOX2, MYC, and NANOG to generate tumor spheres in vitro and tumors in vivo with high frequency." (PMID 38886396, 2024).
tumor (continued). "We compared the expression levels of the CD99, CDKN1A, NES, SOX2, and TUBB3 genes in ES tumor samples and controls consisting of normal muscle tissue." (PMID 38785514, 2024). "Flow cytometry was used to collect GFP+ CD44+ CCs 14 d after tumor cell transplantation, and qRT-PCR was used to examine the expression of CSC markers (Oct4, Abcg2, Sox2, Bmi1, and Ssea1)." (PMID 38625488, 2024). "The difference in SOX2/SOX9 expression and WNT signaling silencing enables tumor cells to enter a quiescent state and to evade the immune clearance by natural killer (NK) cells, finally resulting in propagation into metastasis-establishing cells." (PMID 38275880, 2024). "The 3D osteosarcoma cells were successfully enriched with CSCs, in order to reproduce the CSC-tumor niche behavior, as evidenced by the increased mRNA expression level of stem-related genes, such as OCT-4, SOX-2 and NANOG." (PMID 38791452, 2024). "A KMT2D deficiency leads to reduced phosphoinositide-3-kinase-interacting protein 1 expression and increased phosphorylated AKT, accelerating tumor growth in NSCLC by activating the PI3K/AKT pathway and upregulating SOX2 expression." (PMID 39544292, 2024). "In vitro experiments showed that compared with 2D GC cell culture, the expression of ONECUT2 protein and stemness-related markers CD44, SOX9, SOX2, and LGR4 simultaneously increased in 3D tumor stem cell spheroid culture." (PMID 38997271, 2024). "In the lung sections the expression levels of SOX2 and ALDH1A1 were high in the non-tumor area, relative to the levels in the tumor in both the PLGA-PEI-si-NT and PLGA-PEI-si-m/hVDAC1-B-treated groups." (PMID 39272828, 2024). "DEG analyses revealed the genes contributing to RFS and related to SUVmax (PSG5, TFF3, SOX2, SLC5A5, and SLC5A7) and tumor size (HOXD10, IFNA1, and FER1L6)." (PMID 38745021, 2024). "Taken together, these results show an inverse correlation between N1-ICD and SOX2 expression, yet in three out of four TNBC models, these proteins can be co-expressed within the same tumor and the same cell." (PMID 39478150, 2024). "Expression of radial glial cell signature genes (PAX6, SOX2, FABP7) and FGFR3 was confirmed in both the radial glial/astrocyte-like and tumor cell clusters, whereas PIK3R3 and AKT1 were only expressed in the tumor cell cluster." (PMID 38609519, 2024). "Hypoxia is a key factor in the pathogenesis of gliomas, which enhances tumor development by increasing the expression of stemness (CD133, SOX-2) and drug resistance markers (TIMP-1, Lamp-1) in tumor cells." (PMID 39768176, 2024). "Through the sponging of miR-145–5p, circPTN stimulated glioma stem cells to tumor sphere formation and stemness marker expression like CD133, Nestin, SOX2, and SOX9." (PMID 39170516, 2024). "Nuclear SOX2, nuclear or cytoplasmic BMI1, and membranous or cytoplasmic CD24 or CD166 positivity were observed in the tumor cells of AdCC." (PMID 39858584, 2024). "Mechanistically, let‐7 miRNA can be inhibited by stemness gene LIN28B, which subsequently results in HGMA2 and SOX2 downregulation and finally reduces NEPC tumorigenesis and tumor growth." (PMID 39372390, 2024). "p-AKT enhances the expression of the main stemness-regulating transcription factors (NANOG, OCT-4, and SOX2), anti-apoptotic proteins, and HIF1A-mediated hypoxia, promoting self-renewal, tumor progression, chemoresistance and radioresistance." (PMID 38720782, 2024). "Research indicates that miR-145 exerts anti-stemness and tumor inhibitory effects by directly targeting OCT4, NANOG, SOX2 and KLF4, conversely, these pluripotent TFs can also induce or inhibit the transcription of diverse miRNAs." (PMID 38561775, 2024). "Accordingly, this has spurred the exploration of changes in ALDH-1, SOX2, and HIF-1α in tumor tissues." (PMID 38962320, 2024). "To validate the changes in stemness of the tumor cells processed by the MCTS model, we evaluated the changes in transcription factors (OCT4, NANOG, and SOX2) using qRT-PCR." (PMID 38254728, 2024).